BRCA1 (BRCA1 DNA repair associated)
Diseases named in the same sentence as BRCA1 in open-access papers (continued):
Sharing a sentence is not in itself a finding about the gene and the disease.
ovarian carcinoma (continued). "Despite the increase in throughput using next-generation sequencing (NGS) for BRCA1/2 variant detection, less than 10% of patients with a personal history of breast and/or ovarian cancer received a positive test result." (PMID 36568162, 2022). "The analysis of BRCA1/2 genes in 3,458 patients with breast or ovarian cancer or their relatives revealed 144 carriers of pathogenic variants." (PMID 36171877, 2022). "Loss-of-function mutation of a single allele confers a lifetime risk of ovarian cancer of 40% and 18% for BRCA1 and BRCA2, respectively." (PMID 35159349, 2022). "Mutations of the BRCA1 gene are detected in a significant proportion of families with inherited breast and/or ovarian cancer." (PMID 36479090, 2022). "Ovarian cancer is more related to BRCA1 mutations and tends to develop at an earlier age in these women." (PMID 36230639, 2022). "The epidemiologic evidence strongly supports a significant protective effect of oral contraceptive use on the risk of developing ovarian cancer among women with a BRCA1 or BRCA2 mutation." (PMID 35668475, 2022). "BRCA1 promoter methylation has been associated with favorable response to platinum-based treatment in breast and ovarian cancer which is the standard curative approach in UBC management." (PMID 36076047, 2022). "By using BRCA1/2-mutated breast and ovarian cancer as the references, we observed the wide presence of BRCAness signatures in multiple cancer types." (PMID 36497135, 2022). "Our patient cohort aligned with the expected demographics in epithelial ovarian cancer (largely high-grade serous histology, average age of 65 years, and 17% BRCA1/BRCA2 mutation rate) but was more heavily pretreated than that in the OCEANS trial cohort." (PMID 35972817, 2022). "Strikingly, in ovarian cancer with loss of BRCA1, miR-622 impaired the NHEJ pathway but rescued HR-mediated DSB repair via downregulation of the ku70/ku80 complex during the S phase by inducing resistance to PARPi." (PMID 36253861, 2022). "PARP is considered the potential synthetic lethal partner of BRCA mutations, and its inhibitors are now FDA-approved for the treatment of BRCA1/2-mutated breast and ovarian cancer." (PMID 35330396, 2022). "Approximately 5% to 10% of ovarian cancers are due to inherited germline mutations of susceptible genes, and about 90% of such cases involve mutations of BRCA1 or BRCA2 genes." (PMID 35180738, 2022). "In our previous study, we identified 10 of 158 (6.3%) of unselected cases of ovarian cancer from this region carried one of 13 founder mutations in the BRCA1 or BRCA2 genes." (PMID 35382848, 2022). "Using BRCA1-deficient human ovarian cancer cells, they showed that pretreating these cells with cisplatin before adding a challenging dose of cisplatin yielded diminished RF degradation compared to BRCA1-deficient cells not pretreated with cisplatin." (PMID 36568963, 2022). "Olaparib became the first PARP inhibitor approved by FDA for treating BRCA1/2 mutated ovarian cancer patients who are receiving three or more chemotherapy regimens in 2014." (PMID 35165509, 2022). "Prior studies of matched primary and recurrent BRCA1/2 mutation-associated breast and ovarian cancers have been limited by small numbers (3–8 patients) or focused only on tumors resistant to PARPi, not the entire breadth of frontline therapy and resistance." (PMID 36344544, 2022). "Ovarian cancer patients with BRCA1 or BRCA2 mutations have a better response to platinum chemotherapy and longer progression‐free survival (PFS)." (PMID 38089758, 2022). "Meanwhile, due to its specific genetic background, more than 15% of ovarian carcinoma patients carry germline mutations, and an additional 5–11% of patients carry somatic mutations in either the BRCA1 or BRCA2 gene." (PMID 35887672, 2022). "The breast and ovarian cancer susceptibility gene (BRCA1) is a transcription factor involved in DNA damage repair, cell growth and apoptosis." (PMID 36479090, 2022).
ovarian carcinoma (continued). "To inform clinical management strategies and optimize guidelines for cancer risk management in female and male BRCA1/2 carriers, we comprehensively assess the associations of BRCA1/2 PVs with risks of 22 cancers, other than female breast and ovarian cancers." (PMID 35077220, 2022). "It has been shown that ovarian cancer patients from Poland are characterized by a high proportion of a limited number of recurrent mutations in the BRCA1 gene." (PMID 35382848, 2022). "Rucaparib is another PARP inhibitor being tested for activity in clinical trials in breast and ovarian cancers with germline BRCA1/2 mutations." (PMID 36556296, 2022). "In ovarian cancer patients, there were 52.94% (9/17) and 75.0% (6/8) of pathogenic variants were distributed in exon 14 of BRCA1 and exon 11 of BRCA2, respectively." (PMID 35918668, 2022). "The results demonstrate that ovarian cancer cells deficient in BRCA1 express higher levels of ADRB1, which promotes the synthesis of cAMP." (PMID 35517499, 2022). "The F1CDx assay’s clinical efficacy was supported by bridging to the Foundation Focus CDxBRCA LOH assay in ovarian cancer patients with alterations in BRCA1, BRCA2, or demonstrated genomic loss of heterozygosity (gLOH)." (PMID 35294956, 2022). "Germline BRCA1/2 mutations are identified in 13-15% of ovarian cancers, while an additional 5-7% of ovarian cancers harbor somatic BRCA1/2 mutations." (PMID 36531003, 2022). "Their paper reported that among patients with invasive epithelial ovarian cancer, having a germline mutation in BRCA1/2 was associated with improved 5‐year overall survival and that BRCA2 showed the best prognosis." (PMID 35608067, 2022). "Disruptive BRCA1/2 variants are associated with a predisposition to breast and ovarian cancer, and although at a lower frequency, prostate, pancreas and other cancer types are also linked to pathogenic BRCA1/2 variants." (PMID 35464868, 2022). "Women with germline BRCA1 or BRCA2 (BRCA1/2) mutations have a markedly increased risk of breast and ovarian cancer compared with the general population." (PMID 35409110, 2022). "PARP inhibitors as monotherapy were assessed among germline BRCA1/2-mutated ovarian cancer patients with olaparib (NCT01078662), which showed durable response rates regardless of platinum sensitivity." (PMID 35228986, 2022). "Most of the hereditary ovarian cancers are linked to BRCA1/2 mutations, especially in high-grade serous EOC." (PMID 35805770, 2022). "Carriers of pathogenic BRCA1/2 variants have a higher risk of breast and ovarian cancers, which recur frequently." (PMID 36344544, 2022). "The potent antitumour effects of PARP inhibitors were originally observed in tumours harboring germline BRCA1/2 mutations, such as familial breast and ovarian cancer." (PMID 36010882, 2022). "In other studies, from Norway (190 BOT and 478 ovarian cancer patients) and Canada (134 BOT and 515 ovarian cancer patients), the BRCA1/2 mutations were detected in 4% and 11.7% invasive cases, respectively, but none of the patients with BOT." (PMID 35313928, 2022). "In contrary to our former observation the frequency of BRCA1/2 mutation carriers in the group of ovarian cancer patients is only slightly lower than in other regions of Poland." (PMID 35382848, 2022). "Overall, 67% (n = 2322) of participants expressed willingness to undergo BRCA1/2 testing after being informed about hereditary breast and ovarian cancer risk and BRCA1/2 testing." (PMID 35629239, 2022).
ovarian carcinoma (continued). "To date, only a few surveys on BRCA1/2 mutations in Romanian patients with breast and ovarian cancer have been published." (PMID 35409996, 2022). "The present result was consistent with previous findings such as that ovarian cancer onset in BRCA2 mutation patients was an average 8-10 years later than in patients with BRCA1 mutation." (PMID 35205313, 2022). "We identified 447 DEGs (fold change >1.5, p value <0.05), 176 up-regulated and 271 down-regulated, in the BRCA1-deficient ovarian cancer patients." (PMID 35517499, 2022). "In our former study, we observed that approximately 6% of unselected ovarian cancer patients in the region of Podkarpacie (South-East Poland) carry BRCA1 causative founder variants, which is significantly lower than in other regions of Poland." (PMID 35382848, 2022). "Low-level mosaic epimutations within the BRCA1 gene promoter occur in 5–8% of healthy individuals and are associated with a significantly elevated risk of breast and ovarian cancer." (PMID 37919976, 2022). "Only up to 25% of the cases in which there is a familial aggregation of breast and/or ovarian cancer are explained by germline mutations in the well-known BRCA1 and BRCA2 high-risk genes." (PMID 35595798, 2022). "FDA-approved PARPi has been administered to patients with BRCA1/2-mutated cancers such as breast and ovarian carcinomas." (PMID 36497275, 2022). "Although several founder mutations of the BRCA1 and BRCA2 genes have been reported, the breast and ovarian cancer risks varied by type and location of BRCA1/2 mutations." (PMID 35267543, 2022). "Historically, olaparib became the first PARPi approved by the FDA in December 2014, based on its significant efficacy in the treatment of relapsed ovarian cancer individuals with BRCA1/2 mutations." (PMID 36497275, 2022). "Another study showed that c.4065_4068del is one of the three most common BRCA1 variants in Chinese ovarian cancer patients." (PMID 35918668, 2022). "Germline mutations of the BRCA1 gene have been detected in the majority of familial breast and ovarian cancers." (PMID 35300046, 2022). "Studies in breast and ovarian cancers have shown that patients with BRCA1/2 mutations are responsive to platinum-based chemotherapy." (PMID 35924163, 2022). "PFS was compared in the overall population with ovarian cancer, women with a BRCA1/2 mutation (BRCAm) and women with homologous-recombination deficiency (HRD)." (PMID 35354431, 2022). "Pathogenic variants in BRCA1/2 damage their function, leads to genome instability, and increased the risk of breast and ovarian cancer." (PMID 36497135, 2022). "The prevalence of ovarian cancer in BRCA1 mutation carriers is 1.5% in <40 years of age and increases up to 10–21% by 50 years of age, while in BRCA2 mutation carriers, the risk is less than 3–5% by 50 years of age." (PMID 35267543, 2022). "In breast and ovarian cancer, HR deficiency-associated mutational signatures are predictive of mutations in BRCA1/2 and postulated to be associated with PARP inhibitor response." (PMID 35637530, 2022). "BRCA1-deficient breast and ovarian cancer cells display prominent NDD upon replication arrest by HU." (PMID 36710880, 2022). "Loss of LRRC8D was also a major hit in a genome-scale CRISPR-Cas9 KO screen for cisplatin resistance using BRCA1-mutated ovarian cancer cells." (PMID 36467895, 2022). "In high-grade ovarian cancers with germline BRCA1/2 mutations, almost 50% of platinum-resistant tumors demonstrated secondary mutations in the BRCA1/2 gene." (PMID 35626165, 2022). "On the other hand, the use of oral contraceptives was found to decrease the risk of ovarian cancer in the general population, as well as in BRCA1/2 mutation carriers." (PMID 36072232, 2022). "Inactivating germline mutations of the BRCA1 gene can be detected in a substantial portion of families with inherited breast and/or ovarian cancer." (PMID 35432218, 2022).
ovarian carcinoma (continued). "In ovarian cancer, carrying BRCA1/2 mutations, earlier stage, and lower level of residual tumor after surgery have been proven as predictors of better prognosis for patients receiving platinum-contained chemotherapy." (PMID 35578198, 2022). "PARP inhibitors (PARPi) have increased treatment options in ovarian cancer, particularly in patients with BRCA1/2 mutations, although there are still marked differences in the duration of patients’ response to this targeted therapy." (PMID 36143252, 2022). "The cumulative risk of breast and ovarian cancer for females with the BRCA1/2 gene PV or LPV increases with age, specifically with an estimated penetrance of 60–70% and 20–30% for breast and ovarian cancer, respectively, by the age of 704–6." (PMID 35115620, 2022). "Carriers of pathogenic germline variants in BRCA1/2 have an increased risk of breast and ovarian carcinomas, along with prostate and pancreatic cancers." (PMID 36344544, 2022). "The purpose of this study was to evaluate the cost-effectiveness of olaparib vs. placebo as a maintenance therapy in patients with PSR ovarian cancer with BRCA1/2 mutation from a Chinese healthcare perspective." (PMID 36034834, 2022). "BRCA1/2 mutation frequencies in the 60 Afro-Colombian families affected by breast/ovarian cancer by risk groups." (PMID 35641219, 2022). "Detection of pathogenic germline variants in BRCA1/2 or other risk genes is relevant to the treatment of patients with ovarian cancer and provides an opportunity for cancer prevention in family members." (PMID 35263119, 2022). "The enzymatic inhibition of DNA repair PARPs by small molecules has pioneered a synthetically lethal target therapy strategy for treatment of tumours characterised by DDR defects, such as breast and ovarian cancer carrying BRCA1 and BRCA2 mutations." (PMID 35964058, 2022). "Carriers with BRCA1/2 germline pathogenic variants are associated with a high risk of breast and ovarian cancers (also pancreatic and prostate cancers)." (PMID 36439508, 2022). "Another upcoming study will examine denosumab in ovarian cancer patients with BRCA1 mutation, using immunohistochemistry of patient samples measuring Ki67 as a proliferation index to compare proliferation in denosumab vs. control groups." (PMID 36531159, 2022). "In the current study, we reported for the first time that HMGB3 promoted PARPi resistance in both BRCA1-deficient and wild-type ovarian cancer cells." (PMID 35332131, 2022). "Several studies, which have evaluated the effects of germline BRCA1/2 mutations on epithelial ovarian cancer prognosis, have shown that both PFS and OS were significantly improved in patients with BRCA mutations." (PMID 36612212, 2022). "The accurate classification of BRCA1 variants has a major impact on genetic counseling of carriers and their families, and on the clinical management of patients with breast and ovarian cancer." (PMID 36171434, 2022). "The frequency of BRCA1 or BRCA2 gene mutation carriers among patients with ovarian cancer from the Podkarpacie region is comparable to other regions of Poland." (PMID 35382848, 2022). "Characteristic of ovarian cancers in carriers of the BRCA1 mutation is also an increased risk of fallopian tube and peritoneal cancers, estimated at about 10%." (PMID 35395863, 2022). "The major heritable risk factors for ovarian cancer (OC) are pathogenic germline variants in BRCA1 or BRCA2." (PMID 35456503, 2022). "Characteristics of the Afro-Colombian families affected by breast/ovarian cancer harboring BRCA1/2 mutations and variants." (PMID 35641219, 2022). "The majority (91.4%) of patients had high-grade serous histology, and the population reflected typical ovarian cancer demographics, with a mean age of 65 years and 17% BRCA1/BRCA2 mutation carriers." (PMID 35972817, 2022).
ovarian carcinoma (continued). "A family history of breast or ovarian cancer is associated with an increased risk of leukemia in breast cancer patients, and BRCA1 mutations have been implicated in leukemogenesis." (PMID 36551764, 2022). "For women harboring monoallelic variants that encode dysfunctional BRCA1 protein the cumulative risk for breast or ovarian cancer by the age of 80 years is 72% and 44%, respectively." (PMID 36171434, 2022). "In order to reduce the risk of breast and ovarian cancer, BRCA1/2 germline carriers are encouraged to undergo risk-reducing bilateral salpingo-oophorectomy (rrBSO) upon completion of childbearing, leading to the induction of surgical menopause." (PMID 35685436, 2022). "In this study, through retrospective analysis of ovarian cancer patients’ transcriptome data, we found that ovarian cancer cells in BRCA1-deficient patients expressed higher levels of ADRB1, which can enable adenylyl cyclase to generate cAMP." (PMID 35517499, 2022). "This strategy was effective in patients with ovarian cancers carrying germline or somatic BRCA1/2 mutations." (PMID 35158866, 2022). "Screenwide is a case-control study (2017–2021) including women with incident endometrial and ovarian cancers (EC and OC), BRCA1/2 and MMR pathogenic variant carriers, and age-matched controls from three centers in Spain." (PMID 35887570, 2022). "Diagnostics based only on testing the BRCA1/2 Polish founder mutations is characterized by relatively low sensitivity in the case of ovarian cancer patients from South-East Poland and should be supplemented by NGS study, in particular of the BRCA2 gene." (PMID 35382848, 2022). "BRCA1-null mutations in ovarian cancer cells induce NF-κB signaling, which causes enhanced transcriptional activation of target genes that promote increased autophagy, glycolysis, and oxidative stress in the stroma." (PMID 36531159, 2022). "In this article, we will review the existing epidemiologic evidence regarding the role of contraceptives and the risk of ovarian cancer with a focus on women with a BRCA1 or BRCA2 mutation." (PMID 35668475, 2022). "In a recent Vietnam report of Hoang Anh Vu (2020), there were four types of pathogenic BRCA1 mutations in Vietnamese patients with ovarian cancer." (PMID 35205313, 2022). "BRCA1-mutated ovarian cancers develop resistance to PARPis relatively quickly, commonly through restoration of HR proficiency." (PMID 35501389, 2022). "To date, there has been no official practice guideline for the diagnosis of HBOC syndrome in Vietnam; however, available national guidelines for the treatment of breast and ovarian cancer recommend target therapy for these patients with BRCA1/2 gene mutations." (PMID 35205313, 2022). "Germline mutations in the BRCA1 gene have been reported to increase the lifetime risk of developing breast and/or ovarian cancer (BOC)." (PMID 35409408, 2022). "Breast and ovarian cancer risks differ depending on the position and the type of BRCA1 and BRCA2 mutations." (PMID 36010882, 2022). "In particular, the SNP rs2304277 which causes transcriptional down-regulation of the glycosylase OGG1 is associated with increased ovarian cancer risk for BRCA1 mutation carriers." (PMID 35619904, 2022). "From this side, the poor outcomes of BRCA1-deficient ovarian cancer patients are related to anti-apoptotic ability mediated by ADRB1." (PMID 35517499, 2022). "When to discuss risk-reducing mastectomy in BRCA1/BRCA2 carriers after a diagnosis of advanced stage ovarian cancer can be a challenging area in providing patient-centred genetic counselling." (PMID 36068545, 2022). "Recurrence is a major cause of death among BRCA1/2 mutation carriers with breast (BrCa) and ovarian cancers (OvCa)." (PMID 36344544, 2022). "It has been reported that BRCA1 is closely related to the occurrence of ovarian cancer, and its mutations are the main causes of ovarian cancer." (PMID 36703740, 2022).